GDF15 (growth differentiation factor 15)
Diseases named in the same sentence as GDF15 in open-access papers (continued):
Sharing a sentence is not in itself a finding about the gene and the disease.
glioma (continued). "We found that the protein levels of GDF15 in glioma cell lines were apparently higher than HA." (PMID 34697897, 2022). "Subsequently, we analyzed the effect of GDF15 on progression‐free survival (PFS) of glioma in TCGA." (PMID 34697897, 2022). "It has been shown that GDF15 may influence glioma cell invasion, and elevated level of GDF15 in the cerebrospinal fluid is associated with worse outcome of GBM patients." (PMID 34697897, 2022). "Collectively, GDF15 was up‐regulated in various malignant phenotypes of glioma, suggesting that it may affect glioma prognosis." (PMID 34697897, 2022). "In this study, we suggested that GDF15 play an important role in malignant progression of glioma and the immune microenvironment, and could be served as a novel prognostic and immune related biomarker." (PMID 34697897, 2022). "However, currently, there has not yet been an article comprehensively analyzing the specific clinical and immune features of GDF15 in glioma." (PMID 34697897, 2022). "Interference with GDF15 in several glioma cell lines to verify its functions in vitro." (PMID 34697897, 2022). "GDF15 was up‐regulated in various malignant phenotypes of glioma." (PMID 34697897, 2022). "In this study, we found that GDF15 correlated with malignant progression in glioma using clinical and transcriptome (RNA‐seq) data from two large glioma datasets, including The Cancer Genome Atlas (TCGA) and Chinese Glioma Genome Atlas (CGGA) datasets." (PMID 34697897, 2022). "Therefore, this study examined the role of GDF15, which is one of the cytokines released from the tumor microenvironment, in the cross-talk between ECs and glioma cells irradiated with IR." (PMID 35280749, 2022). "In this study, we first systematically explored the expression of GDF15 in various types of glioma." (PMID 34697897, 2022). "To elucidate the biological functions of GDF15 in glioma, we performed GSEA in TCGA and CGGA." (PMID 34697897, 2022). "Since GDF15 is a member of the TGF-β family, we hypothesized that GDF15 may contribute to the regulation of glioma cell stemness via modulation of LIF–STAT3 signaling." (PMID 33431816, 2021). "Finally, to better understand the molecular mechanism governing RSU-1 and GDF-15 in glioma cells, we proceeded to silence RSU-1 for 24 h and then treated the cells with hrGDF-15 for another 24 h." (PMID 31412547, 2019). "On the other hand, there has been evidence that GDF15 acts as tumor suppressor in glioma cells." (PMID 31412547, 2019). "Also, we found that PINCH1, RhoA and MMP13 play a crucial role being regulated by the RSU-1/GDF15 interplay leading to affection of the final invasive phenotype of glioma cells." (PMID 31412547, 2019). "Similarly, the migration capacity of human and murine glioma cell lines is increased in the presence of ACM, and GDF-15, known to be upregulated in reactive astrocytes, was found to increase proliferation of glioma cells." (PMID 28969644, 2017). "Conversely, an increase in cellular migration and invasion was observed when recombinant GDF-15 was added exogenously which stresses the finding that GDF-15 may critically influence these key properties of glioma cells." (PMID 26741507, 2016). "Furthermore, GDF-15 has been described as an important immunosuppressive cytokine in the context of gliomas and other pathological conditions]." (PMID 26741507, 2016). "Here, we aimed at clarifying the biological role of glioma-derived GDF-15 in more detail." (PMID 26741507, 2016). "Furthermore, ROC analyses performed for glioma cases revealed that the AUC values for the DJ-1, GDF15, and MFGE8 genes were all below 0.7, with p-values above 0.05, indicating that these genes do not have sufficient diagnostic discriminatory power based on patient sex in glioma." (PMID 41009755, 2025). "In addition, GDF15 is correlated with the inflammatory response of glioma and may contribute to an immunosuppressive micro-environment, as well as an immune escape of GBM." (PMID 38201456, 2023).
glioma (continued). "GDF15 could be served as a novel prognostic and immune biomarker for glioma." (PMID 34697897, 2022). "Regulating the expression of GDF15 may help solve the dilemma of immunotherapy in glioma." (PMID 34697897, 2022). "Therefore, we determined whether GDF15 directly modulated proliferation/migration of glioma cells or induced VEGF expression in U373 cells." (PMID 35280749, 2022). "Thus, our results demonstrate that GDF15 can act as a proliferative and pro-stemness factor for GSCs, and therefore, it may represent a potential therapeutic target in glioma treatment." (PMID 33431816, 2021). "Thus, GDF15 signaling may be required for the stemness properties of GSCs and maybe a critical therapeutic target for glioma treatment." (PMID 33431816, 2021). "However, controversy persists regarding the role of GDF15 in different tumor types, and its function in glioma stem cells (GSCs) remains unknown." (PMID 33431816, 2021). "Intrigued by this finding, we wondered whether RSU-1 and GDF-15 are collaborating in regulating glioma cell invasion through a common molecular pathway, as both genes are indirectly associated with actin cytoskeleton reorganization and aggressive cancer cell behavior." (PMID 31412547, 2019). "Overall, elevated expression levels of DJ-1, GDF15, and MFGE8 in glioma and meningioma samples, together with the observed PPI network connections, provide a framework for exploring their potential roles in tumour pathogenesis." (PMID 41009755, 2025). "As a member of the TGFβ superfamily, GDF15 targets CTLA4, a key immune checkpoint protein, thereby promoting glioma progression." (PMID 40535121, 2025). "The interaction between GTPSCS and p300 regulated H3 K18 la and Growth differentiation factor 15 (GDF15) expression, promoting glioma proliferation and radio resistance." (PMID 40484921, 2025). "In our study, a protein–protein interaction (PPI) network analysis was conducted using the GeneMANIA database to further evaluate the potential roles of DJ-1 (PARK7), GDF15, and MFGE8 genes in glioma and meningioma pathogenesis." (PMID 41009755, 2025). "The expression levels of the DJ-1, GDF15, and MFGE8 genes in glioma patients were elevated compared to those in the control group." (PMID 41009755, 2025). "In this study, significant and marked increases in the expression levels of the DJ-1, GDF15, and MFGE8 genes were detected in both glioma and meningioma tissues." (PMID 41009755, 2025). "According to TCGA and CGGA datasets, DJ-1, GDF15, and MFGE8 were found to be highly expressed in gliomas." (PMID 41009755, 2025). "In this study, the gene expression profiles of DJ-1, GDF15, and MFGE8 in tissue samples obtained from glioma and meningioma patient groups were found to be elevated compared to those in the control group." (PMID 41009755, 2025). "Correlation analysis revealed that TSPAN4 was positively correlated with ITGB1, GDF15, ITGA3 and ITGA6, and negatively correlated with CHD7, ASPDH, TMEM8B and GHITM in glioma." (PMID 39723210, 2024). "Previous studies reported that GDF15 is required for the activation of STAT3 and tumorigenesis in thyroid cancer and glioma stem cells." (PMID 36769245, 2023). "IR promotes GDF15 secretion from the ECs, which leads to the secretion of VEGF from the glioma cells." (PMID 35280749, 2022). "GDF-15 is also an active area of study in cancer immunity, and GDF-15 has been shown to allow gliomas to evade immune responses by suppressing natural killer cell-mediated immunity and T cell migration into the tumors." (PMID 35821815, 2022). "We showed that glioma cells behave differently with regard to cell migration and invasion depending on the relative RSU-1 and GDF15 expression." (PMID 31412547, 2019). "This, combined with the fact that GDF15 is involved in actin cytoskeleton organization, prompted us to investigate the interplay between this protein and RSU-1 with regard to glioma cell aggressiveness in vitro." (PMID 31412547, 2019).
glioma (continued). "It is known that GDF-15 affects the activity of the uroplasminogen activation system in LNT-229 and LN-308 glioma cells." (PMID 29467963, 2018). "In order to gain more insights into the autocrine effects of glioma-derived GDF-15, we assessed the miRNA and mRNA expression profiles upon GDF-15 gene silencing in LNT-229 and LN-308 cells." (PMID 26741507, 2016). "We confirmed GDF-15 mRNA expression in a panel of 8 human long-term glioma cell (LTC) lines and 5 glioma-initiating cell (GIC) lines in vitro." (PMID 26741507, 2016). "In this study, the expression levels of DJ-1, GDF15, and MFGE8 genes were assessed in glioma and meningioma samples, and the resulting data were associated with clinical and pathological parameters, including sex, Ki-67 Pi, tumour diameter, and WHO tumour grade." (PMID 41009755, 2025). "Integrating PPI-based findings with gene expression data may contribute to understanding the possible mechanistic roles of DJ-1, GDF15, and MFGE8 in glioma and meningioma biology." (PMID 41009755, 2025). "The clinical and immune features for GDF15 in glioma have not been specifically investigated so far." (PMID 34697897, 2022). "Interestingly, the overall survivals of lower grade glioma (LGG), mesothelioma (MESO), and uveal melanoma (UVM) patients were significantly correlated with the GDF15 level." (PMID 35853851, 2022). "To analyze the impact of GDF15 on GSCs, we established patient-derived and glioma cell line-derived TS cells, and the cells with GSC-like characteristics were utilized as GSCLCs in studies of glioma stemness in vitro." (PMID 33431816, 2021). "In an attempt to elucidate the interplay between GDF15 and RSU-1 in glioma cell invasion and the molecular pathway involved, we first assessed the invasion capacity of H4, SW1088 and A172 cells using a 3-dimensional (3D) spheroid formation assay in collagen following RSU-1 silencing." (PMID 31412547, 2019). "GDF15 belongs to the Transforming Growth Factor β (TGFβ) superfamily of cytokines, and it is found to be elevated in the serum of patients with high grade gliomas representing a negative prognostic factor." (PMID 31612114, 2019). "Moreover, high GDF15 expression was significantly related to EGFR and chromosome 7 copy number amplification, as well as PTEN and chromosome 10 copy number reduction, which were both markers of poor prognosis for glioma." (PMID 34697897, 2022). "However, the clinical and immune features for GDF15 in glioma have not been specifically investigated so far." (PMID 34697897, 2022). "Moreover, GDF15 is downregulated in aggressive glioma cell lines (SW1088 and A172) in contrast to non-aggressive neuroglioma cells (H4) and its expression is exactly opposite from that of RSU-1 in glioma cells." (PMID 31412547, 2019). "In the present study, we characterized the autocrine function of GDF-15 using comprehensive approaches including large-scale miRNA and mRNA expression profiling upon gene silencing, thereby aiming at defining the impact of GDF-15 on the malignant phenotype of glioma cells." (PMID 26741507, 2016). "Interestingly, a dramatic increase in GDF15 mRNA expression was observed following RSU-1 silencing in A172 glioma cells, which have low endogenous GDF15 levels versus non-specific control (NSC) sample, while a smaller increase was observed in H4 cells, which have higher endogenous GDF15 levels." (PMID 31412547, 2019).
hepatocellular carcinoma (37 papers, 2011 to 2026). A malignant tumor that arises from hepatocytes. "CD48 can participate in GDF15-induced regulatory T cell generation and enhanced function, thereby regulating hepatocellular carcinoma-associated immunosuppression." (PMID 37285836, 2023). "Elevated GDF15 levels correlate with advanced stages of fibrosis, suggesting that GDF15 could be used to identify patients at higher risk of progressing to severe liver diseases, including cirrhosis and hepatocellular carcinoma." (PMID 39697329, 2024). "The other 6 proteins tested were chosen because of their reported involvement in liver diseases (e.g. GDF15, which has been shown to be involved in liver disease and hepatocellular carcinoma) and other cancers (as is the case for CEA, IGFBP2, B2M, PDGF-Rb and OPN)." (PMID 30220970, 2018). "Proteomic analysis of urinary exosomes from 18 hepatocellular carcinoma patients and healthy controls by mass spectrometry revealed increased expression of OLFM4, HDGF, and GDF15 in patients with hepatocellular carcinoma." (PMID 40075875, 2025). "Another study in the literature found that the AUC value for GDF-15 (AUC = 0.693) was lower than in our study for distinguishing between hepatocellular carcinoma patients and healthy individuals." (PMID 41157623, 2025). "In liver cancer models, hepatic stellate cells secrete GDF15 to stimulate hepatoma cell proliferation, while HCC-derived GDF15 facilitates the generation of inducible Treg cells, contributing to an immunosuppressive tumor microenvironment." (PMID 40677718, 2025). "In bladder cancer cells, ectopically upregulating NDRG1 decreased cells proliferation and invasion in a GDF15-dependent manner, while in hepatocellular carcinoma, LINC01419 promotes cell proliferation and metastasis by enhancing NDRG1 promoter activity." (PMID 38271137, 2024). "It was also reported that hepatoma cells secrete growth differentiation factor 15 (GDF15) by enhancing the autophagy of interstitial hepatic stellate cells and promoting the proliferation of hepatoma cells." (PMID 38039297, 2023). "In hepatocellular carcinoma (HCC) tissues, GDF15 was reported to be positively associated with elevated Treg cell frequency." (PMID 36472770, 2023). "GDF15 was also found to promote immunosuppression by enhancing the generation of Tregs in hepatocellular carcinoma." (PMID 36353620, 2022). "In one study of hepatocellular carcinoma cells, GDF15 was found to increase Tregs mediated by CD48, leading to immunosuppression." (PMID 36353620, 2022). "In contrast, Gdf15 is a downstream target of Pvt1 and was positively regulated by the lncRNA in hepatocellular carcinoma cells." (PMID 34364390, 2021). "They showed that co-culturing with hepatoma cells (HepG2, Hep3B, Huh7) increased GDF15 expression in the LX-2s, which was attenuated by knocking out ATG7 in the LX-2s." (PMID 34885024, 2021). "Serum GDF-15 levels were significantly increased in patients with liver cirrhosis and hepatocellular carcinoma." (PMID 34777864, 2021). "In stem cells derived from hepatocellular cancer, GDF-15 induced AKT/GSK-3β/β-catenin signaling, which would, again, be tumor-promoting." (PMID 32508832, 2020). "Similar observations linking GDF-15 to anorexia/cachexia were made in various other conditions such as hepatocellular carcinoma." (PMID 32508832, 2020). "In hepatocellular carcinoma, GDF-15 was found to enhance cell viability, invasion, metastasis, and hepatitis C virus (HCV) replication." (PMID 32508832, 2020). "This study also, for the first time, offers evidence that increased GDF15 expression promotes JFH-1 based HCVcc replication in cultured hepatoma cells." (PMID 21625435, 2011). "Overexpression of GDF15 in hepatoma cells resulted in increased DNA synthesis, promoted cell proliferation, and importantly enhanced invasiveness of the cells." (PMID 21625435, 2011).
hepatocellular carcinoma (continued). "Similarly, it has been demonstrated that hepatoma cells induced LX-2 cells secreting more growth differentiation factor 15 (GDF15) in an autophagy-dependent manner to enhance hepatoma cells proliferation." (PMID 37007125, 2023). "Consequently, GDF15 blockade resulted in hepatocellular carcinoma clearance through an enhanced antitumor immune response." (PMID 36353620, 2022). "The mRNA expression and protein secretion of GDF15 was dramatically increased in HCV-infected hepatoma cells, which maybe a host response to viral proteins or infection-induced cell stress." (PMID 21625435, 2011). "Meanwhile, GDF15 showed an enhancement of hepatoma cell proliferation." (PMID 21625435, 2011). "It has been reported in the literature that GDF-15 levels correlate with the severity of liver fibrosis and are significantly elevated in the serum of patients with complications such as cirrhosis and hepatocellular carcinoma arising from chronic HBV infections." (PMID 41157623, 2025). "In other models of cancer that respond poorly to immunotherapy, such as hepatocellular carcinoma (HCC), GDF15 is also an ideal target because it plays a central role in the generation and activation of Tregs, thereby mediating an immunosuppressive response." (PMID 36353620, 2022). "In the present study, we identified the up-regulation of GDF15 in HCV-infected hepatoma cells and evaluated serum levels of GDF15 in cohorts of patients with chronic hepatitis C or hepatitis B. Additionally, we investigated the biological impact of increased GDF15 on hepatoma cells." (PMID 21625435, 2011). "The mitokines, fibroblast growth factor 21 (FGF21) and growth differentiation factor 15 (GDF15), are overexpressed during mtUPR activation and are positively correlated with hepatocellular carcinoma progression." (PMID 40943612, 2025). "In hepatocellular carcinoma (HCC), GDF15 promotes angiogenesis via Src signaling and suppresses anti-tumor immunity by enhancing immune cell suppressive functions." (PMID 40868185, 2025). "Expression patterns of GCNT3, GDF15, and HMOX1 in Huh7 and L-02 cells after C. pilosula or A. membranaceus treatments were similar to those in hepatocellular carcinoma HepG2 cells." (PMID 30936938, 2019). "The expression patterns of GCNT3, GDF15, and HMOX1 in Huh7 and L-02 cells after treated with qi-tonifying herbs were similar to those in hepatocellular carcinoma HepG2 cells." (PMID 30936938, 2019). "Likewise, the upregulation of GDF15 is correlated with severity and poor clinical outcomes of hepatitis B virus (HBV) infection in patients with hepatocellular carcinoma." (PMID 36140453, 2022). "◊Induced by HCV infection and regulates hepatocellular carcinoma-related genes.◊Genetic ablation of GDF-15 has no apparent effect on HCC tumor formation rate, growth rate or invasiveness." (PMID 36675666, 2022). "However, a clinical relevance has not been reported between serum GDF15 level and severe liver diseases, such as hepatocellular carcinoma and cirrhosis." (PMID 25996938, 2015). "Gdf15 is induced in humans with liver cirrhosis and hepatocellular carcinoma, while several BMPs, which are members of the TGFβ superfamily, are induced in NASH, cirrhosis and HCC." (PMID 28422962, 2017).